GABARAP (GABA type A receptor-associated protein)
Diseases named in the same sentence as GABARAP in open-access papers (continued):
Sharing a sentence is not in itself a finding about the gene and the disease.
Sepsis (4 papers, 2016 to 2025). Sepsis is defined as life-threatening organ dysfunction caused by a dysregulated host response to infection. "This study revealed that GABARAP expression was increased in a diagnostic model of sepsis combined with ALF." (PMID 40781631, 2025). "GABA type A receptor-associated protein (GABARAP) deficiency led to increased susceptibility to sepsis through the enhancement of mtROS and proinflammatory cytokine expression with NLRP3 inflammasome activation." (PMID 32922385, 2020). "This study reveals the potential value of GABARAP and ITCH as diagnostic biomarkers associated with pyroptosis in sepsis and ALF." (PMID 40781631, 2025). "Here we demonstrate that GABARAP autophagy proteins negatively regulate GBP2-dependent caspase-11 inflammasome activation to prevent sepsis." (PMID 33042141, 2020). "Taken together, these data indicate that GABARAP autophagy proteins are important for the suppression of caspase-11-dependent sepsis." (PMID 33042141, 2020). "We found GABARAP and ITCH may serve as diagnostic biomarkers for pyroptosis in sepsis combined with ALF, suggesting their potential involvement in the initiation and advancement of sepsis combined with ALF through cellular immunomodulatory pathways." (PMID 40781631, 2025). "Machine learning revealed that GABARAP and ITCH may serve as diagnostic biomarkers for pyroptosis in sepsis combined with ALF." (PMID 40781631, 2025). "In addition, there is a paucity of research regarding the correlation between GABARAP and ALF, with barely any research validating the role of GABARAP in sepsis combined with ALF." (PMID 40781631, 2025). "GABARAP deficiency impairs mitochondrial homeostasis in macrophages and enhances mitochondrial ROS generation, hence exacerbating NLRP3 inflammasome-dependent inflammatory responses and contributing to critical pathogenic processes in sepsis." (PMID 40781631, 2025). "Machine learning indicated that GABARAP and ITCH may be hub genes implicated in the pathological mechanisms of sepsis and ALF." (PMID 40781631, 2025). "In conclusion, GABARAP and ITCH may serve as promising pyroptosis-related diagnostic biomarkers for sepsis and ALF." (PMID 40781631, 2025). "Animal experiments further validated that in the process of sepsis combined with ALF, the expression level of GABARAP is elevated, while the expression level of ITCH is diminished." (PMID 40781631, 2025). "Considering the intricate relationship between immune cells and sepsis as well as ALF, the correlation of GABARAP and ITCH with various immune cells was analyzed." (PMID 40781631, 2025). "Taken together, these data demonstrate that GABARAP autophagy proteins specifically limit GBP2-dependent caspase-11 inflammasome activation and sepsis." (PMID 33042141, 2020). "The examination of immune cell infiltration indicated that immune dysregulation is present in both sepsis and ALF and preliminarily suggested that GABARAP and ITCH may be pivotal in cellular immunity responses, particularly those mediated by T cells." (PMID 40781631, 2025). "GABARAP and ITCH may have extensive regulatory effects on numerous biological pathways, particularly concerning cellular immune function, which could impact the pathogenesis of sepsis combined with ALF." (PMID 40781631, 2025). "Additionally, further animal experiments have indicated that GABARAP and ITCH may mediate the pathogenesis of sepsis combined with ALF." (PMID 40781631, 2025).
epilepsy (3 papers, 2019 to 2020). A brain disorder characterized by episodes of abnormally increased neuronal discharge resulting in transient episodes of sensory or motor neurological dysfunction, or psychic dysfunction. "Coimmunoprecipitation analysis revealed protein–protein interactions between protrudin, GABAARβ2/3 and GABARAP in the hippocampus of PTZ-induced epilepsy mice." (PMID 31772151, 2019). "Furthermore, protrudin upregulated cell surface GABAAR protein expression, possibly by affecting GABAAR transport through its interaction with GABARAP in epilepsy." (PMID 31772151, 2019). "Kinesin family member 5A (KIF5A) has been reported to regulate neuronal surface expression of GABA(A)Rs via an interaction with GABA(A)R-associated protein (GABARAP), indicating that KIF5A could be involved in inhibitory neural transmission regulation related to epilepsy." (PMID 33718116, 2020).
hepatocellular carcinoma (3 papers, 2022 to 2025). A malignant tumor that arises from hepatocytes. "A long noncoding RNA, nuclear paraspeckle assembly transcript 1 (NEAT1) variant 1 (NEAT1v1), confers radioresistance to hepatocellular carcinoma (HCC) cells by inducing autophagy via γ-aminobutyric acid A receptor-associated protein (GABARAP)." (PMID 36430876, 2022). "There is evidence that a long non-coding RNA (lncRNA), nuclear-enriched abundant transcript 1 (NEAT1) variant 1 (NEAT1v1), could promote autophagy through GABARAP and lead to radio-resistance of hepatocellular carcinoma (HCC) cells." (PMID 40900801, 2025).
neuroblastoma (3 papers, 2010 to 2025). Neuroblastoma (NB) is the most common solid, extracranial childhood tumor. "Previous results using RT–qPCR analysis on 235 neuroblastomas showed that lower GABARAP expression levels were associated with more advanced stages." (PMID 20197771, 2010). "Similarly, decreased expression of GABARAP and GABAergic gene family members have been associated with poor outcome in a subset of neuroblastoma patients." (PMID 37532697, 2023).
Obesity (3 papers, 2019 to 2022). Accumulation of substantial excess body fat. "Accordingly, whether the severe HFD‐induced obesity HFD phenotype determined by AC3 VMH cilia expression was caused by GABARAP‐mediated autophagy requires further study." (PMID 34783461, 2022). "Thus, our results might indicate a potential link between ciliary AC3 expression and GABARAP‐associated autophagy in response to HFD‐induced obesity in the mouse VMH." (PMID 34783461, 2022). "In contrast to the SCD feeding results, the VMH GABARAP KD mice showed more pronounced HFD‐induced obesity than the controls." (PMID 34783461, 2022). "Mice with GABARAP knockdown in the VMH exhibit exacerbated HFD‐induced obesity." (PMID 34783461, 2022). "Therefore, we cannot rule out potential effects other than cilia and noncanonical autophagy in the phenotype of the more pronounced HFD‐induced obesity of VMH GABARAP KD mice." (PMID 34783461, 2022).
Alzheimer disease (2 papers, 2023 to 2025). A progressive, neurodegenerative disease characterized by loss of function and death of nerve cells in several areas of the brain leading to loss of cognitive function such as memory and language. "The aim of this study was to further investigate the role of genes identified in our previous studies as relevant for the pathophysiology of Alzheimer’s disease and T2DM comorbidity, namely ATG16L1, ATG16L2, GABARAP, GABARAPL1, GABARAPL2, and SQSTM1." (PMID 36901549, 2023).
coronary heart disease (2 papers, 2019 to 2025). "Furthermore, we determined the molecular mechanism underlying Granule of BU-XIN RUAN-MAI-regulated GABARAP expression in the treatment of coronary heart disease." (PMID 31949464, 2019). "miR-542-3p exhibited the ability to protect against the pectoris of coronary heart disease by regulating GABARAP." (PMID 41296393, 2025). "MiR-542-3p/GABARAP axis is required for Granule of BU-XIN RUAN-MAI exhibiting its protective activity against pectoris of coronary heart disease." (PMID 31949464, 2019). "Then, miR-542-3p can significantly promote oxidation and inflammation in cardiomyocytes of coronary heart disease by targeting GABARAP." (PMID 31949464, 2019). "To explore the role of miR-542-3p/GABARAP axis in coronary heart disease, we examined the effects of miR-542-3p/GABARAP axis on oxidation and inflammation." (PMID 31949464, 2019). "Together, these findings indicate that miR-542-3p may aggravate oxidation and inflammation in coronary heart disease by targeting GABARAP, and miR-542-3p/GABARAP axis is required for Granule of BU-XIN RUAN-MAI showing its protective activity against angina pectoris of coronary heart disease." (PMID 31949464, 2019). "Interestingly, overexpression of GABARAP may improve the development of coronary heart disease by promoting autophagy which can attenuate the anginal pectoris of heart disease." (PMID 31949464, 2019). "The miR-542-3p/GABARAP axis is required for Granule of BU-XIN RUAN-MAI, exhibiting its protective activity against the pectoris of coronary heart disease." (PMID 31949464, 2019). "Moreover, the silencing of GABARAP could obviously reverse the granule of BU-XIN RUAN-MAI-mediated protective activity against coronary heart disease, and interfering GABARAP expression also could partly block the anti-miR-542-3p-controlled oxidation and inflammation in cardiomyocytes." (PMID 31949464, 2019). "GABARAP has been considered as a novel and essential regulator that it could improve coronary heart disease including angina pectoris and arteriosclerosis by increasing autophagy, which is a beneficial biological process for treatment of coronary heart disease." (PMID 31949464, 2019).
dementia with Lewy bodies (2 papers, 2022). "An assessment of mammalian ATG8 orthologues in the spinal cord and cortical tissue from PD and dementia with Lewy bodies (DLB) patients found that ~40% of LBs were immune-positive for LC3-II, whereas only ~15% stained positive for GABARAP/GABARAPL1." (PMID 35216492, 2022). "Recently, LC3, GABARAP, and GATE-16 have been reported in Parkinson’s disease (PD) and dementia with Lewy bodies (DLBs)." (PMID 36699066, 2022).
HIV-1 infection (2 papers, 2025). The type species of lentivirus and the etiologic agent of acquired immunodeficiency syndrome (AIDS). "Further studies are warranted to investigate TFEB localization and phosphorylation status, as well as the expression and activity of IRGM and GABARAP proteins, in the context of vitamin D3 supplementation during HIV-1 infection." (PMID 40514685, 2025). "Furthermore, during HIV-1 infection, mammalian ATG8 homologs (mAtg8s), particularly GABARAP, orchestrate a finely tuned regulatory network involving lysosomal biogenesis and immune restriction." (PMID 40568704, 2025).
lung adenocarcinoma (2 papers, 2021 to 2024). A carcinoma that arises from the lung and is characterized by the presence of malignant glandular epithelial cells. "Next, we investigated the protein levels of GABARAP and GABARAPL1 by IHC in 60 samples of lung adenocarcinomas." (PMID 34681055, 2021).
lung carcinoma (2 papers, 2024 to 2025). "AM-101 activates the GABA(A) receptor in lung cancer cells, triggering selective autophagy by causing GABARAP to form multimers and stabilizing the mitochondrial receptor Nix." (PMID 39335139, 2024).
pancreatic cancer (2 papers, 2017 to 2025). "Bioinformatic analysis of human tumours revealed that several core autophagy genes, including GABARAP, correlate with oncogenic KRAS mutations and poor prognosis in human pancreatic cancer, supporting a potential tumour-suppressive effect of the pathway in Ras-driven human cancers." (PMID 28581519, 2017).
angina pectoris (1 paper, 2019). The symptom of paroxysmal pain consequent to MYOCARDIAL ISCHEMIA usually of distinctive character, location and radiation. "Thus, we investigated whether GABARAP was involved in the Granule of BU-XIN RUAN-MAI-induced inhibition of angina pectoris." (PMID 31949464, 2019).
atherosclerosis (1 paper, 2021). A disease characterized by the build-up of fatty material and calcium deposition in the arterial wall resulting in partial or complete occlusion of the arterial lumen. "Impaired autophagy aggravates atherosclerosis, and may serve as a link between GABARAP and PAD." (PMID 34616426, 2021).
diabetic cardiomyopathy (1 paper, 2024). Diabetic cardiomyopathy is a disorder of the heart muscle in people with diabetes. "We constructed a diagnostic model of DCM, and OXCT1, CACNA2D2, BCL7B, EGLN3, GABARAP, and ACADSB were potential biomarkers, which may provide new insights for improving the ability of early diagnosis and treatment of diabetic cardiomyopathy." (PMID 38469146, 2024). "We found diagnostic and predictive biomarkers of type 2 DCM consisting of OXCT1, CACNA2D2, BCL7B, EGLN3, GABARAP, and ACADSB, which may reduce the difficulty of early prediction of diabetic cardiomyopathy, and lay a foundation for prospective research." (PMID 38469146, 2024).
hearing loss (1 paper, 2025). "Our findings underscore the critical role of GABARAP in AG ototoxicity and highlight its potential as a therapeutic target for preventing AG-induced hearing loss." (PMID 39928869, 2025). "We previously reported that GABARAP and several other central autophagy proteins are essential for AG-induced hearing loss." (PMID 39928869, 2025). "This study, using genetic approaches along with morphological and functional assays, reveals that both GABARAPL1 and GABARAP are essential for AG-induced hearing loss, with GABARAP playing a more prominent role." (PMID 39928869, 2025). "Thus, it is critical to identify additional proteins in the RIPOR2/GABARAP signaling pathway to provide additional targets for preventing AG-induced hearing loss." (PMID 39928869, 2025). "RIPOR2, an AG-binding protein previously identified in hair cells, is essential for AG-induced hearing loss, as is the RIPOR2/ GABARAP-mediated autophagy pathway." (PMID 39928869, 2025). "Another possibility is that, despite sharing 87% amino acid identity, GABARAP and GABARAPL1 may have slightly different functions in autophagy pathway and AG-induced hearing loss." (PMID 39928869, 2025).
intraductal carcinoma (1 paper, 2021). "The expression of GABARAP in normal breast tissue, intraductal carcinoma and invasive ductal carcinoma was detected using IHC." (PMID 33591943, 2021).
melanoma (1 paper, 2016). A malignant, usually aggressive tumor composed of atypical, neoplastic melanocytes. "Finally, tumor growth of B16 melanoma cells after subcutaneous inoculation was inhibited in GABARAP-deficient mice." (PMID 27124579, 2016). "Finally, our results provide evidence for the role of autophagy in anti-tumor immunity, as we showed that B16 melanoma cells' growth in GABARAP KO mice is reduced." (PMID 27124579, 2016).
nicotine addiction (1 paper, 2018). "Although GABARAP showed no health risk, its involvement in nicotine addiction suggested the potential formation of TSNAs from nicotine and development of cancer." (PMID 29616208, 2018).
osteosarcoma (1 paper, 2025). A usually aggressive malignant bone-forming mesenchymal neoplasm, predominantly affecting adolescents and young adults. "This consistent association underscored the potential of GABARAP as a robust predictor of clinical outcomes in osteosarcoma patients." (PMID 41346635, 2025). "Its spatial enrichment in metabolic and immunosuppressive niches underscores its pathogenic significance, positioning GABARAP as a potential therapeutic target and biomarker of aggressive osteosarcoma." (PMID 41346635, 2025). "Colony formation assays corroborated these findings, showing marked reductions in both colony quantity and size, indicating the essential role of GABARAP in osteosarcoma cell proliferation." (PMID 41346635, 2025). "In osteosarcoma, where chemoresistance often correlates with metabolic rewiring, these functions provide a plausible mechanism for GABARAP-mediated therapy resistance." (PMID 41346635, 2025). "Consistent with recent findings that autophagy is indispensable for osteosarcoma growth and therapy adaptation, GABARAP appears to coordinate mitochondrial quality control with metabolic resilience." (PMID 41346635, 2025). "In this study, GABARAP emerged as a pivotal factor in osteosarcoma progression through its dual roles in mitophagy and metabolic regulation." (PMID 41346635, 2025). "Collectively, these findings establish GABARAP as a central regulator of osteosarcoma cell proliferation, migration, and metabolic fitness, operating through mitophagy modulation and pyruvate metabolic reprogramming." (PMID 41346635, 2025). "To elucidate the spatial distribution and functional implications of GABARAP, mitophagy, and pyruvate metabolism in osteosarcoma, we performed spatial transcriptomic profiling of primary osteosarcoma TME." (PMID 41346635, 2025). "To investigate the functional significance of GABARAP in osteosarcoma, we generated stable knockdown models in 143B and U2OS cells using lentivirus-mediated shRNAs (shGABARAP#1 and shGABARAP#2)." (PMID 41346635, 2025). "Functionally, GABARAP depletion disrupted mitophagy flux, mitochondrial integrity, and energy production, thereby impairing osteosarcoma cell proliferation and migration." (PMID 41346635, 2025). "Wound healing assays demonstrated impaired migratory capacity in GABARAP-silenced cells, demonstrating that GABARAP may contribute to the migratory potential of osteosarcoma cells." (PMID 41346635, 2025). "Functional validation established GABARAP as a central oncogenic regulator orchestrating synergistic mitophagy flux and pyruvate metabolic reprogramming, thereby identifying GABARAP as a promising therapeutic target for osteosarcoma progression." (PMID 41346635, 2025). "Considering the effect of GABARAP on mitophagy in osteosarcoma, we next explored the expression of several key mitophagy-associated genes, including BNIP3, PINK1, Parkin, LC3B, p62, and Beclin1, which were significantly downregulated in GABARAP knockdown cells." (PMID 41346635, 2025). "Finally, the impact of GABARAP on osteosarcoma progression has yet to be validated in vivo or in clinical settings." (PMID 41346635, 2025). "Then, we further assessed the prognostic value of GABARAP and BNIP3 in three independent osteosarcoma cohorts, TARGET-OS, GSE21257, and GSE32981, respectively." (PMID 41346635, 2025). "Given its diverse roles across cancers, strategies aimed at modulating GABARAP activity, either inhibiting its tumor-supportive functions or exploiting its capacity to induce lethal stress responses, may offer translational opportunities in osteosarcoma and other malignancies." (PMID 41346635, 2025). "The autophagy-related protein GABARAP, central to mitochondrial quality control, has not been systematically evaluated in osteosarcoma." (PMID 41346635, 2025).
ovarian carcinoma (1 paper, 2024). A malignant neoplasm originating from the surface ovarian epithelium. "We employed a small peptide that had been designed to target the protein GABARAP and inhibit autophagy in ovarian cancer cells by blocking Nix binding." (PMID 39335139, 2024).
prostate carcinoma (1 paper, 2022). A carcinoma that arises from epithelial cells of the prostate gland. "Among mammalian autophagy proteins, the Atg8 family member GABARAP has been shown to be greatly involved in the autophagy process of prostate cancer cells, supporting the idea that GABARAP inhibitors could be valuable tools to fight the progression of tumors." (PMID 35563459, 2022).
Salmonella Infections (1 paper, 2026). Infections with bacteria of the genus SALMONELLA. "Relative to OP50 feeding, colonization with B. longum resulted in the suppression of forkhead box protein O (daf-16), LC3, GABARAP and GATE-16 family (lgg-1), and beclin homolog 1 (bec-1), leading to the attenuation of autophagy in C. elegans in response to Salmonella infection." (PMID 41347508, 2026).
thyroid cancer (1 paper, 2019). "In addition, CDH6 was reported to interact with autophagy-related proteins GABA Type A Receptor-Associated Protein (GABARAP), BCL2 Interacting Protein 3 (BNIP3) and BNIP3L to restrict autophagy and to promote the reorganization of the mitochondrial network in thyroid cancer cells." (PMID 31324051, 2019).